STAT3 (signal transducer and activator of transcription 3)
Diseases named in the same sentence as STAT3 in open-access papers (continued):
Sharing a sentence is not in itself a finding about the gene and the disease.
head and neck cancer (continued). "Here, we found that inhibition of EGFR by erlotinib results in phosphorylation of STAT3 at Tyr705 leading to its activation and to increased levels of Bcl2/Bcl-XL at both mRNA and protein levels in head and neck cancer cells." (PMID 24019973, 2013). "Treatment of Tu212 and Tu686 head and neck cancer cells with erlotinib reduced PTPMeg2 (i.e. a physiologic STAT3 phosphatase) in a time-dependent manner." (PMID 24019973, 2013). "Niclosamide, as a STAT3 inhibitor, can block erlotinib-induced phosphorylation of STAT3 leading to synergistic suppression of head and neck cancer." (PMID 24019973, 2013). "Specific knockdown of STAT3 by RNA interference significantly sensitized head and neck cancer cells to erlotinib treatment." (PMID 24019973, 2013). "Pharmacological inhibition of STAT3 by niclosamide not only blocked erlotinib-stimulated STAT3 phosphorylation but also synergistically repressed head and neck cancer growth in vitro and in vivo." (PMID 24019973, 2013). "EGFRvIII has been reported to mediate head and neck cancer cell migration and invasion by increasing STAT3 activation." (PMID 24376686, 2013). "These QD-IHF data not only provide additional evidence that erlotinib activates STAT3, but also uncover the molecular mechanism by which niclosamide and erlotinib synergistically repress head and neck cancer in vivo." (PMID 24019973, 2013). "STAT3 has been recently identified as a potential therapeutic target for the treatment of head and neck cancer." (PMID 24019973, 2013). "In head and neck cancer, resistance is also mediated by TLR4-MyD88 signaling activation, loss of tumor suppressor genes like PTEN, activating mutations in PI3K, and involvement of STAT3." (PMID 40560045, 2025). "Additionally, the phosphorylation level of STAT3 can modulate the response of regulatory T cells (Tregs) to radiation therapy in head and neck cancer." (PMID 38650924, 2024). "With regard to gastric, lung, and head and neck cancers, which we examined in this study, previous reports showed that STAT3 activation was associated with negative factors such as poor prognosis of cancers." (PMID 34679602, 2021). "DEX was reported to reduce VEGF secretion in some head and neck cancer cells via STAT3." (PMID 32033410, 2020). "It has been shown that STAT3 modulates the abundance and function of regulatory T (Treg) cells in response to radiation therapy in head and neck cancer, suggesting that STAT3 inhibition may be beneficial for patients receiving radiation." (PMID 32972405, 2020). "Indeed, a regulatory mechanism between STAT3 and P38 has been described in head and neck cancer, whereby STAT3 phosphorylation requires P38; however, additional experiments would be required to assess if this is also the case in GC cells." (PMID 32252293, 2020). "STAT3 is constitutively hyperactivated in many cancers, including head and neck cancers." (PMID 33206698, 2020). "There is evidence that in head and neck cancer, the NF‐κB transcriptional factor is constitutively activated and linked to activation of known oncogenic pathways, such EGFR/Ras/RAF/MAPK, Akt/PI3K/mTOR, ΙΚΚ/NF‐κB, STAT3 and wnt/β‐catenin." (PMID 29911313, 2018). "In vitro studies showed that EGCG inhibited cisplatin-induced ROS, ERK1/2 and STAT1 activation in UMSCC head and neck cancer cells, but had little effect on cisplatin-induced inhibition of STAT3, Bcl-2 and Bcl-xL levels or the observed increases in cleaved caspase-3." (PMID 28703809, 2017). "To determine whether STAT3 pathway expression was associated with human HNSCC, we interrogated the Oncomine database to explore the gene expression of STAT3 in head neck cancer." (PMID 26556875, 2015). "We also examined the STAT3 activation mediated through IL-6 in head and neck cancer." (PMID 24533098, 2014). "This could be a direct effect of H-4073 on FAK phosphorylation or indirectly mediated through STAT3 as we have previously shown that STAT3 can regulate FAK activation in head and neck cancer cells." (PMID 24675768, 2014).
head and neck cancer (continued). "Silencing of STAT3 not only downregulates Bcl2 and Bcl-XL but also significantly sensitizes head and neck cancer cells to erlotinib, suggesting that targeting STAT3 may have great potential to improve the efficacy of erlotinib against head and neck cancer." (PMID 24019973, 2013). "Depletion of STAT3 by RNAi significantly sensitizes head and neck cancer cells to erlotinib." (PMID 24019973, 2013). "In summary, the present studies have demonstrated that inhibition of EGFR by erlotinib stimulates phosphorylation and activation of STAT3 leading to increased levels of Bcl2 and Bcl-XL, which could reduce the efficacy of erlotinib against head and neck cancer." (PMID 24019973, 2013). "Importantly, specific knockdown of PTPMeg2 also led to increased STAT3 phosphorylation and elevated levels of Bcl2 and Bcl-XL in head and neck cancer cells, which further supports the role of PTPMeg2 as a physiologic STAT3 phosphatase, as recently reported." (PMID 24019973, 2013). "Intriguingly, specific knockdown of PTPMeg2 also activated the STAT3/Bcl2/Bcl-XL survival pathway, suggesting that PTPMeg2 may play an important role in regulating the sensitivity of erlotinib to head and neck cancer cells." (PMID 24019973, 2013). "In addition to its important role in oncogenesis, STAT3 is also involved in modeling of cancer stem cells (CSCs) of various origins, including breast, lung, pancreas, and head and neck cancers, suggesting that STAT3 inhibition is an approach to enhancing CSC-targeted therapy in human cancers." (PMID 27145367, 2016). "However, it has been observed in numerous studies that STAT3 is constitutively active in a variety of human solid tumors including lung cancer, prostate cancer, breast cancer and in more than 95% of head and neck cancers." (PMID 24675768, 2014). "Here, we found that inhibition of EGFR by erlotinib stimulated phosphorylation and activation of STAT3 leading to increased Bcl2/Bcl-XL expression in head and neck cancer cells, which may dampen the therapeutic efficacy of erlotinib against head and neck cancer." (PMID 24019973, 2013). "Combined inhibition of EGFR and STAT3 using erlotinib and niclosamide synergistically represses head and neck cancer in vitro and in vivo, which may represent a novel and effective therapeutic strategy for improving prognosis of patients with head and neck cancer." (PMID 24019973, 2013). "STAT3 is a promoter of MDSC immune regulatory activity and can be induced by radiation, along with PD-1, based on studies in head and neck cancer." (PMID 40427227, 2025). "The Oncomine database was utilized to analyze the expression of MET, STAT3, and AKT in head and neck cancer and normal tissue samples." (PMID 37373393, 2023). "The TCGA head and neck cancer statistics were filtered, and it was discovered that MET, STAT3, and AKT gene expressions were greater than those in the control group." (PMID 37373393, 2023). "We mined the TCGA’s head and neck cancer genomics data using the c-BioPortal website to study the roles of MET, STAT3, and AKT overexpression." (PMID 37373393, 2023). "In head and neck cancer, MET expression was significantly correlated with STAT3 (r = 0.269) and AKT (r = 0.503)." (PMID 37373393, 2023). "Our functional assays revealed that the anti-STAT3 mcDNA, 48 h post-transfection, has a promising IC50 of 13.48 nM - a low nanomolar concentration comparable or superior to previously reported decoy molecules used in head and neck cancer models." (PMID 41031165, 2025). "In addition, the Human Protein Atlas database was utilized to confirm the histological levels of MET, STAT3, and AKT, and the results indicate that these genes were elevated in head and neck cancer tissue relative to normal tissue." (PMID 37373393, 2023).
head and neck cancer (continued). "STAT3 knockdown resulted in decreased orosphere-forming ability of HNSCC cells in ultralow attachment plates, suggesting the importance of STAT3 signaling to the survival and self-renewal of head and neck cancer stem cells." (PMID 29245982, 2017). "A number of studies have shown that IL-6 promotes head and neck cancer cell proliferation, migration, survival, invasion, epithelial to mesenchymal transition (EMT), stem cell expansion, and chemoresistance via the activation of JAK/STAT3 signaling pathway." (PMID 28107179, 2017). "High‐throughput screens of HPV‐positive and negative head and neck cancers showed differences in the gene expression patterns, which correlated to STAT3/NF‐кB/AP‐1 signaling pathway." (PMID 28155253, 2017). "Recently, our preliminary data indicate both Stat-3/Nanog and JNK/c-Jun pathways can be simultaneously activated in the upregulation of miR-21 expression during HA/CD44-mediated signaling in both breast cancer cells and head and neck cancer cells." (PMID 27070574, 2016). "STAT3, a member of the STAT family of transcription factors, is activated in several cancers, and has recently been validated as an attractive therapeutic target in cancer therapy, including head and neck cancer." (PMID 24019973, 2013). "STAT1, STAT3 and STAT5 proteins are frequently overexpressed in head and neck cancer cell lines." (PMID 23708675, 2013). "Furthermore, IL-6 independent STAT3 activation can be found in other cancers, including head and neck cancers and haemopoietic cancers, suggesting that not all cancers that have high STAT3 activity necessarily have high IL-6 expression." (PMID 31226168, 2019). "Gene expression analysis across multiple cell lines found Wnt signaling and STAT3 among genes whose expression correlates with resistance to chemo-radiation or radiation while combining radiation with a chemical inhibitor for STAT5 reduced survival in head and neck cancer cell lines." (PMID 27584613, 2016).
asthma (103 papers, 2005 to 2026). "Mechanistically, IL-6-driven STAT3 signaling has been implicated in steroid resistance and persistent airway inflammation in Th17-skewed asthma models, reinforcing the clinical importance of these cytokine patterns." (PMID 41601686, 2026). "Immunodeficiency was present in 37.5% of cases, most commonly hyper-IgE syndrome (HIES)/Job syndrome (28%), followed by STAT1/STAT3 mutations, juvenile idiopathic arthritis, asthma, DAVID syndrome, diffuse proliferative glomerulonephritis, and ALL." (PMID 41149903, 2025). "Collectively, the downregulation of STAT3 expression and its associated signaling pathways likely underlie Res’s therapeutic effects in asthma treatment." (PMID 40453664, 2025). "CYBB (AUC ═ 0.82), EPAS1 (AUC ═ 0.839), CBS (AUC ═ 0.804), G6PD (AUC ═ 0.86), and STAT3 (AUC ═ 0.873) demonstrate high diagnostic accuracy for asthma (AUC > 0.8)." (PMID 40165005, 2025). "In conclusion, CYBB, EPAS1, CBS, G6PD, and STAT3 demonstrate strong diagnostic potential for asthma." (PMID 40165005, 2025). "Asthma is mainly caused by airway inflammation, and STAT3 involved in inflammatory and immune response plays an important role in the pathogenesis of asthma." (PMID 39444792, 2024). "A study in mice showed that lung inflammation can be caused by STAT3 via accelerating the development of Th17 cells and promoting the production of cytokines by Th2 and Th17 cells, which will lead to the occurrence of asthma." (PMID 39444792, 2024). "Airway epithelial STAT3 plays a key role in the occurrence of asthma, and its activation is associated with asthma symptoms such as airway hyperresponsiveness and lung and airway inflammation." (PMID 39444792, 2024). "STAT3 upregulation and activation in the airways are closely associated with the onset and development of asthma, while STAT3 activation facilitates TSLP in asthma-associated airway remodeling." (PMID 36172292, 2022). "In fact, previous studies have shown that STAT3 is activated in asthma, and its activity is associated with airway remodeling, airway inflammation, and AHR." (PMID 34341336, 2021). "STAT3 is an important transcription factor that has been found to be implicated in airway inflammation and remodeling in asthma." (PMID 31913462, 2020). "IL-5 induced STAT3/5 signaling plays a causative role in allergic asthma and is being targeted by Mepolizumab, which proves to be quite effective in reducing risk of asthma exacerbations as well as reduce dependence on corticosteroids." (PMID 30081609, 2018). "Recently, STAT3 was implicated in asthma pathogenesis in a study that showed that STAT3-dependent pathways induced by IL-13 in lung myofibroblasts were inhibited by the administration of the inhaled corticosteroid, fluticasone." (PMID 15935090, 2005). "In this report, we present our analysis of the association of STAT3 SNPs with lung function in adults with asthma, and replicate our findings in a cohort of children with asthma." (PMID 15935090, 2005). "Single nucleotide polymorphisms (SNPs) in STAT3 were genotyped and tested in a screening dataset from an adult asthma clinical trial." (PMID 15935090, 2005). "STAT3 single-nucleotide polymorphism is associated with decreased lung function in asthma patients." (PMID 40453664, 2025). "Bioinformatics analyses identified STAT3 as a key ferroptosis-related gene implicated in asthma." (PMID 40165005, 2025). "As the JAK2/STAT3 pathway is preferentially activated by IL-6, prevention of IL-6/JAK2/STAT3 signaling may be associated with the anti-inflammatory effects of H. cuspidatus treatment of asthma." (PMID 35572723, 2022). "We hypothesized that the mechanism of ZKPC against asthma could be associated with JAK2/STAT3 pathway." (PMID 34608825, 2021).
asthma (continued). "The results of a clinical study on patients with STAT3 mutations may be pertinent given the known inhibitory effect of shikonin on STAT3 expression in the airway epithelium of murine asthma models (discussed previously) and the dual function of STAT3 in MC degranulation." (PMID 41560747, 2025). "Indeed, the loss of STAT3 expression within the airway epithelium decreased the expression of Th2 cytokines, lowered airway inflammation and prevented the development of airway hyperreactivity in an asthma model." (PMID 24101903, 2013). "The NLRP3 inflammasome also regulates ferroptosis in asthma inflammation through the JAK2/STAT3 pathway." (PMID 41550926, 2025). "Zisuzi Decoction ameliorates AHR and partially reverses airway remodeling through inhibition of PI3K/AKT1/mTOR, JAK2/STAT3, and HIF‐1α/NF‐κB signaling pathways, demonstrating effectiveness in cough‐variant asthma management." (PMID 41426510, 2025). "CIAPIN1 plays a role in the PI3K/AKT and JAK2/STAT3 signaling pathways, making it a promising candidate for therapeutic interventions to manage asthma." (PMID 40338178, 2025). "Bioinformatics identified STAT3 and EPAS as key genes closely linked to ferroptosis, with their expression significantly upregulated in asthma and positively correlated with each other." (PMID 40165005, 2025). "Collectively, these results underscore the pivotal role of STAT3 in driving ferroptosis and inflammatory responses in IL-13-treated 16HBE cells, offering new insights into the pathogenesis of asthma." (PMID 40165005, 2025). "This study highlights the critical role of the JAK2/STAT3-EPAS axis in asthma through a combination of bioinformatics analysis and experimental validation." (PMID 40165005, 2025). "Inhibition of STAT3 has been reported to reduce eosinophilic infiltration, cytokine release, and airway hyperresponsiveness in asthma models, while also attenuating IL-6-mediated inflammatory signaling and airway remodeling in COPD." (PMID 41304567, 2025). "Severe Th2-driven atopic dermatitis and asthma are common in several IEIs, including DOCK8 deficiency, STAT3 loss-of-function, and Wiskott–Aldrich syndrome, often refractory to conventional therapies." (PMID 41357247, 2025). "In summary, activation of STAT3 can reverse the inhibitory effect of shikonin on the function of MLE-12 cells, confirming that the inhibitory effect of shikonin on asthma is dependent on STAT3." (PMID 39444792, 2024). "Shikonin mitigates asthma symptoms through a STAT3-dependent mechanism, indicating its potential as an anti-asthmatic therapeutic agent." (PMID 39444792, 2024). "Considered together, m6A-YTHDF1 plays a complex role in the pathological process of inflammatory response in the NA asthma subtype through the regulation of the macrophage JAK2/STAT3 signaling pathway." (PMID 39108751, 2024). "Suppression of STAT3 prevents the production of IL‐4, IL‐13, and IL‐17, which are upregulated in asthma." (PMID 38286741, 2024). "To further confirm the inference that shikonin can alleviate asthma by regulating STAT3, we observed the effect of shikonin on the expression and localization of p-STAT3 in TNF-α-induced mouse epithelial cell line MLE-12." (PMID 39444792, 2024). "The specific knockout of STAT3 expressed in airway epithelial cells can significantly down-regulate house dust mite (HDM)-induced airway inflammation in asthma mice." (PMID 39444792, 2024). "Previous studies have demonstrated the involvement of STAT3 signaling pathway activation in airway remodeling during asthma." (PMID 38708080, 2024). "The role of STAT3 in asthma is still controversial, as some reports have indicated that the STAT3 level is elevated in asthma, while others have found that blocking this signaling pathway improves asthmatic symptoms." (PMID 38286741, 2024). "STAT3 plays an essential role in the production of inflammatory cytokines and is one of the important mechanisms leading to airway inflammation in asthma." (PMID 39444792, 2024).